RBM7 (RNA binding motif protein 7)
Diseases named in the same sentence as RBM7 in open-access papers:
RBM7 is named in the same sentence as 12 diseases in open-access papers, as found by Europe PMC text mining. Sharing a sentence is not in itself a finding about the gene and the disease. The quoted sentences say what the papers report.
breast carcinoma (4 papers, 2017 to 2024). "We then conducted qRT-PCR analysis of theses metastasis-associated genes in RBM7-depleted breast cancer cells and verified that they were up-regulated upon RBM7 knockdown shown as heatmap representation." (PMID 38995840, 2024). "Cancer metastasis is comprised of a complex cascade of events, such as migration, invasion and angiogenesis, thus we next to determine which process is mediated by RBM7-loss in facilitating breast cancer metastasis." (PMID 38995840, 2024). "RBM7 knockdown enhanced aggressiveness of breast cancer relying on MFGE8 splicing switch to the short variant and NF-κB pathway activation." (PMID 38995840, 2024). "Decreased RBM7 expression was associated with poor prognosis of breast cancer." (PMID 38995840, 2024). "Breast cancer cells with loss of RBM7 gain enhanced aggressive capability and metastatic potential." (PMID 38995840, 2024). "This meant that the overexpression of RBM7 could cause the proliferation and growth of the breast cancer cells by affecting he process of cell cycle (*P < 0.05)." (PMID 33145401, 2020). "RBM7 was upregulated in breast cancer and associated with poor survival." (PMID 33145401, 2020). "We also obtained paired primary breast cancer and lymph node metastatic loci and found, when compared to the corresponding primary tumor, the expression of RBM7 is significantly decreased in lymph node metastases." (PMID 38995840, 2024). "Nevertheless, in our study, RBM7 knockdown in breast cancer displayed visibly pro-metastasis function with activated NF-κB signaling." (PMID 38995840, 2024). "Currently, the pathobiological function of RBM7 in breast cancer is underexplored except one study that claimed an oncogenic role of RBM7 since its knockdown inhibited breast cancer cell proliferation." (PMID 38995840, 2024). "(G–J) The metastatic ability of breast cancer cells with RBM7 depletion (G) or ectopic expression of RBM7 (I) were evaluated by transwell assay." (PMID 38995840, 2024). "(C) The expression of RBM7 in primary breast carcinoma (n=1097) compared to normal tissues (n=114) was analyzed through UALCAN dataset." (PMID 38995840, 2024). "Similar results were obtained in two additional TNBC cell lines BT549 and HCC1937, which proved that RBM7 possessed the capability to suppress the migration and invasion of breast cancer cells." (PMID 38995840, 2024). "(F) The mechanistic model of how RBM7 regulated metastasis of breast cancer through regulating MFGE8 splicing switch." (PMID 38995840, 2024). "Taken together, these data above indicated that both MFGE8 splice switch and NF-κB pathway activation are required for mediating the pro-metastasis activity of RBM7 reduction in breast cancer." (PMID 38995840, 2024). "Analysis of TCGA, GEO and the METABRIC breast cancer datasets showed that RBM7 expression positively correlates with overall survival of breast cancer patients." (PMID 38995840, 2024). "Breast cancer cells with RBM7 depletion exhibited an increased potential for lung metastasis compared to scramble control cells." (PMID 38995840, 2024). "This is coherent with decreased RBM7 expression levels found in breast cancer with lymph node metastasis." (PMID 38995840, 2024). "Next, we sought to assess if MFGE8 splicing switch is responsible for acquisition of aggressive feature in RBM7-silenced breast cancer cells." (PMID 38995840, 2024). "Meanwhile, the migrative and invasive ability of breast cancer cells treated with ASOs was significantly boosted, further suggesting that RBM7-knockdown stimulated aggressiveness of breast cancer at least partially relies on the control of MFGE8 AS." (PMID 38995840, 2024). "Overall, our findngs implicated that activated NF-κB pathway worked in concert with MFGE8 splicing transition to spur metastasis in RBM7-depleted breast cancer." (PMID 38995840, 2024).
breast carcinoma (continued). "More importantly, according to TCGA database (total cases >1,000 used for analysis), RBM7 shows decreased expression in breast cancer, particularly in the metastasis loci and has positive correlation with patients’ survival outcomes." (PMID 38995840, 2024). "To examine the impact of RBM7 on angiogenesis in breast cancer, we cultured human umbilical vein endothelia cells (HUVEC) with condition medium obtained from culture supernatants of RBM7-depleted or scramble shRNA transduced cells for tube formation analysis." (PMID 38995840, 2024). "(C) A heatmap showing the qRT-PCR analysis of differentially expressed genes upon RBM7 knockdown in breast cancer cells from three biological replicates." (PMID 38995840, 2024). "In this study, we report that RBM7 is frequently reduced in a subset of breast cancer metastases from lymph nodes lesions and distant organ as compared to primary tumors and its low expression predicts dismal survival outcomes of patients." (PMID 38995840, 2024). "Additionally, although the detailed clinical significance underlying their cooperation need further in-depth investigation, we propose that RBM7 and its regulated splicing variants might serve as potential therapeutic biomarker and prognostic indicator in breast cancer patients." (PMID 38995840, 2024). "Using whole-transcriptome sequencing, we found the depletion of RBM7 contributed to exon exclusion in approximately 70% SE/A5E events, implying RBM7 mainly functions as a splicing activator in the context of SE/A5E in breast cancer." (PMID 38995840, 2024). "RBM7-targeted silencing for breast cancer would likely be detrimental for neighbouring heathy tissue and immune environment as a result of NF-κB-dependent pro-inflammatory mediators and cytokines secretion." (PMID 38995840, 2024). "To determine the clinical relevance of RBM7 in breast cancer, we assessed the correlation between RBM7 and important clinical outcomes." (PMID 38995840, 2024). "RBM7 promoted breast cancer cell proliferation by stabilizing CDK1 mRNA via binding to AREs in its 3'-UTR." (PMID 34804951, 2021). "In breast cancer cells, knocking down the RBM7 gene also inhibits cell proliferation, and induces G1 cell cycle arrest." (PMID 34804951, 2021). "Herein, we attempted to clarify the biological function of RBM7 in breast cancer, and investigated its potential molecular mechanism by identifying its key mRNA targets." (PMID 33145401, 2020). "In vitro, experiments revealed that knockdown of RBM7 dramatically inhibited breast cancer cell proliferation, while inducing G1 cell cycle arrest; the opposite was true when RBM7 was overexpressed." (PMID 33145401, 2020). "The survival curve data of RBM7 from the Human Protein Atlas revealed that upregulation of RBM7 was correlated with poorer prognosis (Log-rank P-value i = 2.90e−3 < 0.05) in breast cancer patients." (PMID 33145401, 2020). "All the evidences implied RBM7 promoted breast cancer cell proliferation by stabilizing CDK1 mRNA via binding to AREs in its 3′-UTR." (PMID 33145401, 2020). "In vitro, knockdown of RBM7 dramatically inhibited breast cancer cell proliferation, while inducing G1 cell cycle arrest; the opposite was true when the expression of RBM7 was overexpressed." (PMID 33145401, 2020). "All the evidences implied RBM7 promoted breast cancer cell proliferation by stabilizing CDK1 mRNAs via binding to AREs in its 3′-UTR." (PMID 33145401, 2020). "Owing to Sh-1, Sh-2 showed the efficiencies ≥85% of RBM7 knockdown in breast cancer cells, they were selected for the further study." (PMID 33145401, 2020). "Similar to the results from the cell lines, the expression of RBM7 in breast cancer tissues was significantly elevated relative to the adjacent normal breast tissues by quantitative real-time PCR (RT-qPCR) (*P < 0.05) and Western blot." (PMID 33145401, 2020).
breast carcinoma (continued). "RBM7 expression in breast cancer cells including SUM-1315, MDA-MB-231, MCF-7, ZR-75-1, and BT474 cells was found to be higher than that in human normal mammary epithelial cell line MCF-10A at mRNA (*P < 0.05) and protein levels." (PMID 33145401, 2020). "This indicated that RBM7 expression had a positive relationship with CDK1 expression in breast cancer tissues." (PMID 33145401, 2020). "RBM7 negatively regulated breast cancer metastatic potential." (PMID 38995840, 2024). "It is therefore highly doubtful that RBM7 could serve as an oncogene in breast cancer as previously reported." (PMID 38995840, 2024). "In concert, NF-κB inhibitor abolished pro-angiogenesis effect of RBM7 ablation in breast cancer." (PMID 38995840, 2024). "Compared to the scramble control, HUVEC incubated with culture medium from RBM7-knockdown breast cancer cells exhibited accelerated tube formation length and branch junction, suggesting the inhibitory effect of RBM7 on breast cancer angiogenesis." (PMID 38995840, 2024). "Further investigation is warranted to elaborate more splicing mechanisms of RBM7 in breast cancer." (PMID 38995840, 2024). "Thus, we performed tail-vein transfer model to evaluate the potential impact of RBM7 on pulmonary metastasis of breast cancer cells." (PMID 38995840, 2024). "We next performed immunohistochemistry (IHC) detection of RBM7 in breast cancer tissue microarrays." (PMID 38995840, 2024). "Congruently, we found RBM7 is decreased in breast cancer compared to normal tissues." (PMID 38995840, 2024). "This is coherent with the nuclear localization of RBM7 in breast cancer cells." (PMID 38995840, 2024). "Here, we unveiled that RBM7 is decreased in lymph node and distant organ metastases of breast cancer as compared to primary lesions and low expression of RBM7 is correlated with the reduced disease-free survival of breast cancer patients." (PMID 38995840, 2024). "RBM7 low expression predicts the reduced disease-free survival in patients with breast cancer." (PMID 38995840, 2024). "In addition, we collect specimen consisted of tumor tissues from 21 breast primary cancer, in 9 cases, from metastatic loci and took advantage of IHC analysis to determine the RBM7 expression." (PMID 38995840, 2024). "In the present study, RBM7 firstly served as a breast cancer oncogene." (PMID 33145401, 2020). "It indicated CDK1 was a main target of RBM7 exhibiting its oncogenic activity in breast cancer." (PMID 33145401, 2020). "Meanwhile, experiments in vivo confirmed the oncogenic function of RBM7 in breast cancer." (PMID 33145401, 2020). "Finally, IHC revealed that CDK1 expression was higher in RBM7 higher expressed breast cancer tissues (*P < 0.05)." (PMID 33145401, 2020). "Moreover, upregulated expression of RBM7 in breast cancer tissues was positively correlated with poor prognosis, implying its potential prognostic value for breast cancer patients." (PMID 33145401, 2020). "All these results strongly supported that RBM7 acted as an oncogenic role in breast cancer." (PMID 33145401, 2020). "To ascertain the functional targets that explain the inhibitory role of RBM7 in breast cancer metastasis, we analyzed RNA immunoprecipitation sequencing data for RBM7 and whole-transcriptome sequencing data for breast cancer cells expressing two shRNAs targeting RBM7." (PMID 38995840, 2024). "Moreover, we can’t exclude additional biological function of RBM7 in breast cancer." (PMID 38995840, 2024). "All these implied that RBM7 could significantly affect the expression of CDK1 in breast cancer." (PMID 33145401, 2020). "(A–B) The correlation between RBM7 mRNA expression and overall survival (OS) or disease-free-survival (DFS) of breast cancer patients (n=1980) was analyzed based on the METABRIC dataset." (PMID 38995840, 2024). "However, the specific function of RBM7 in human breast cancer remains unclear." (PMID 33145401, 2020).
breast carcinoma (continued). "RBM7, an RBP in one of RNA exosome cofactors (NEXT complex), was gradually confirmed as a key regulatory role in breast cancer development." (PMID 33145401, 2020). "However, the role of RBM7 in cancers, especially in breast cancer, is still unknown." (PMID 33145401, 2020). "Above all, our findings uncovered a previously unidentified role of RBM7 in breast cancer metastasis via coupling MFGE8 splicing switch and NF-κB signaling activation, suggesting a new therapeutic target and prognostic predictor for breast cancer." (PMID 38995840, 2024). "In tissue chip containing triple negative breast cancer, the more aggressive and mesenchymal breast cancer subtype, RBM7 exhibits reduced protein levels in tumors as compared to paracancer tissues." (PMID 38995840, 2024). "Further dissection in a cohort of breast cancer patients from the cBioPortal unveiled cases with lymph node metastasis have lower expression of RBM7 as compared to cases without metastasis." (PMID 38995840, 2024). "In separate experiments, we transfected breast cancer cells with an exogenous MFGE8 splicing reporter containing exon 6–8 and 600 bp of flanking intron sequences to determine the splicing regulatory function of RBM7." (PMID 38995840, 2024). "RNA-seq data showed that the depletion of RBM7 resulted in a significant alteration in ratio of MFGE8 two isoforms, of which the canonical isoform (MFGE8-L) has been demonstrated to be correlated with tumor formation and aggressiveness of breast cancer." (PMID 38995840, 2024). "(D) Analysis of RBM7 expression in breast cancer lymph node metastases in comparison with breast cancer tissues with no lymph node metastasis based on TCGA dataset." (PMID 38995840, 2024). "The abnormal expression of RBM7, described as a key component in nuclear exosome cofactor (NEXT complex), could show the oncogenic activities in breast cancer due to its RBP activities." (PMID 33145401, 2020). "The absence of RBM7 stimulated breast cancer cell migration, invasion, and angiogenesis." (PMID 38995840, 2024).
spinal muscular atrophy (3 papers, 2018 to 2024). A motor neuron disease that affect the muscles, and characterized by muscle weakness and atrophy resulting from progressive degeneration and irreversible loss of the anterior horn cells in the spinal cord (i.e., lower motor neurons) and the brain stem nuclei. "Recessive variants in exosome components EXOSC3, EXOSC8, and RBM7 cause various constellations of pontocerebellar hypoplasia (PCH), spinal muscular atrophy (SMA), and central nervous system hypomyelination." (PMID 34573300, 2021). "Recessive variants in exosome components EXOSC3, EXOSC8, and RBM7 cause various constellations of pontocerebellar hypoplasia (PCH), spinal muscular atrophy (SMA), and central nervous system demyelination." (PMID 29727687, 2018).
breast tumor (1 paper, 2024). "At another layer, RBM7 reduction led to NF-κB pathway activation, resulting in enhancement of breast tumor aggressiveness." (PMID 38995840, 2024).
Myotonia (1 paper, 2025). An involuntary and painless delay in the relaxation of skeletal muscle following contraction or electrical stimulation. "Interestingly, several splicing factors including Srsf6, Prpf39, Rbm7, Tra2b, Rbfox2, and Hnrnpu, exhibited alternative splicing in Mbnl1−/− mice with myotonia, but not in those without." (PMID 41000779, 2025).
triple-negative breast carcinoma (1 paper, 2024). An invasive breast carcinoma which is negative for expression of estrogen receptor (ER), progesterone receptor (PR), and human epidermal growth factor receptor 2 (HER2). "(F) Representative images of the IHC staining of RBM7 in a tissue microarray containing triple-negative breast cancer (n=119) and para-carcinoma tissues (n=20)." (PMID 38995840, 2024).
cancer (4 papers, 2017 to 2024). A tumor composed of atypical neoplastic, often pleomorphic cells that invade other tissues. "Aberrant expression of RBM7 is not only associated with lung fibrosis onset and motor neuronopathy, but also impacts cancer cell proliferation." (PMID 38995840, 2024). "The RT-PCR analysis demonstrated that the PSI of selected gene related to cancer progression was either increased or decreased endogenously upon RBM7 depletion." (PMID 38995840, 2024). "While some members play the opposite role, promoting cell proliferation and the invasion of cancer, including RBM7, RBM11, and RBM15." (PMID 34804951, 2021). "Hence, we offer a framework for anti-cancer approaches consisting of targeting RBM7 and P-TEFb together with DNA-damaging chemotherapeutics." (PMID 30824372, 2019). "Lacking of RBM7 has been also reported to be associated with DNA damage hypersensitivity that can linked to cancer predisposition." (PMID 28977914, 2017). "However, the mechanistical role of RBM7 in cancer remain largely unknown." (PMID 38995840, 2024).
tumor (2 papers, 2020 to 2024). "Other splicing events switch triggered by RBM7 might also be linked to tumor development." (PMID 38995840, 2024). "Most (25% strong positive;67% moderate positive) of primary tumor samples displayed a positive IHC staining for RBM7, whereas most of lung/liver metastatic lesions showed weak or negative RBM7 expression." (PMID 38995840, 2024). "The time required for tumor formation in the RBM7 overexpression group was significantly shorter than that in the control group (*P < 0.05)." (PMID 33145401, 2020). "The tumor was found obviously in control group after 8 days, and the tumors from the RBM7 overexpression group were found less than 8 days." (PMID 33145401, 2020).
RBM7 also shares sentences with these, for which no sentence is quoted: pontocerebellar hypoplasia (2 papers); Cerebellar hypoplasia (1); COVID-19 (1); fibrosis (1); lymph node metastasis (1).